FBXO21 (F-box protein 21)
Description:
Substrate-recognition component of the SCF (SKP1-CUL1-F-box protein)-type E3 ubiquitin ligase complex.
Synonyms: FBX21; KIAA0875
Tractability: PROTAC: ubiquitination databases record sites on it; its protein half-life has been measured.
Safety:
Unwanted effects reported when the protein is acted on. In parentheses: how it was acted on, where the effect was seen, and who reports it.
neutropenia (source: ClinPGx)
Gene: Protein-coding gene on chromosome 12 (117,141,991 to 117,190,504, reverse strand). Ensembl gene ENSG00000135108.
Subcellular location (Human Protein Atlas): Centrosome; Cytosol; Basal body; Primary cilium; Primary cilium tip
Pathways (Reactome):
Immune System: Antigen processing: Ubiquitination & Proteasome degradation
Metabolism of proteins: Neddylation
Gene Ontology:
Molecular function: protein binding; ubiquitin-protein transferase activity; DNA binding
Biological process: SCF-dependent proteasomal ubiquitin-dependent protein catabolic process; ubiquitin-dependent protein catabolic process
Cellular component: cytosol; SCF ubiquitin ligase complex; ubiquitin ligase complex
Genetic constraint (gnomAD): Loss-of-function variants: 31 observed, 72.24 expected, observed/expected ratio (o/e) 0.43, 90% interval 0.32 to 0.58. The upper end of that interval is the gene's LOEUF score, 0.58, which puts it in group 2 of 6, group 1 being the genes least tolerant of losing a copy. Missense variants: 519 observed, 748.84 expected, observed/expected ratio (o/e) 0.69, 90% interval 0.64 to 0.75. Synonymous variants: 297 observed, 293.01 expected, observed/expected ratio (o/e) 1.01, 90% interval 0.92 to 1.12.
Homologues: Orthologues: chimpanzee FBXO21 (100% identical), rabbit FBXO21 (99% identical), dog FBXO21 (99% identical), pig FBXO21 (98% identical), rat Fbxo21 (96% identical), mouse Fbxo21 (95% identical), macaque FBXO21 (91% identical), zebrafish fbxo21 (58% identical), tropical clawed frog fbxo21 (56% identical).
Diseases named in the same sentence as FBXO21 in open-access papers:
FBXO21 is named in the same sentence as 17 diseases in open-access papers, as found by Europe PMC text mining. Sharing a sentence is not in itself a finding about the gene and the disease. The quoted sentences say what the papers report.
osteoarthritis (5 papers, 2021 to 2023). A noninflammatory degenerative joint disease occurring chiefly in older persons, characterized by degeneration of the articular cartilage, hypertrophy of bone at the margins and changes in the synovial membrane. "Additionally, downregulation of FBXO21 alleviated osteoarthritis-associated cartilage degeneration, which accompanied with promotion of autophagy and anabolism, reduction of apoptosis as well as catabolism." (PMID 37359559, 2023). "Ageing rats and monosodium iodoacetate-driven osteoarthritis rats exhibited an increased expression of FBXO21 in cartilages." (PMID 37359559, 2023). "JunB binds directly to the promoter region of FBXO21, accelerates cartilage degeneration, and further regulates osteoarthritis apoptosis through the JunB-FBXO21-ERK axis." (PMID 37483616, 2023). "They reported that osteoarthritis patient cartilages had higher expression of FBXO21." (PMID 37359559, 2023). "Hence, FBXO21 plays a potential role in osteoarthritis development." (PMID 37359559, 2023). "FBXO21 and circRNA-MSR expression levels were increased in osteoarthritis, while miR-761 expression levels were decreased in osteoarthritis." (PMID 37359559, 2023). "A previous study demonstrated that FBXO21/ERK is related to the occurrence of osteoarthritis, and ERK is one of the novel binding partners of FBXO21 detected in osteoarthritis." (PMID 36443856, 2022). "In a word, JUNB/FBXO21/ERK pathway governs cartilage degeneration via blockade of autophagy in osteoarthritis, indicating that downregulation of FBXO21 might be a novel approach for osteoarthritis treatment." (PMID 37359559, 2023).
viral infection (3 papers, 2016 to 2021). "Both FBXO21 and TRIM65 are necessary for the production of type I IFNs in response to viral infection." (PMID 33956915, 2021). "In mice study, FBXO21 was found to facilitate Lys29-linkage and activation of ASK1 (apoptosis signal-regulating kinase 1) and promote type I interferon production upon viral infection." (PMID 32038701, 2019). "We found that the interaction of Fbxo21-ASK1 was increased 0.5–2 hr after virus infection, and was then decreased 3–4 hr after virus infection, indicating that the potential modulation of ASK1 by Fbxo21 mainly occurred within 0.5–2 hr after virus infection." (PMID 27063938, 2016). "In Fbxo21-/- RAW264.7 cells reconstituted with Fbxo21, we found that Fbxo21 could promote the linkage of K29O-Ub to ASK1 after virus infection." (PMID 27063938, 2016). "Our study suggests that SCFFbxo21 may be the ligase responsible for Lys29-linkage of ASK1 by demonstrating that Fbxo21 is required for Lys29-linkage of ASK1 upon viral infection, leading to non-proteolytic modification of ASK1 and ASK1 phosphorylation." (PMID 27063938, 2016). "Here we report that F-box only protein Fbxo21, a functionally unknown component of SCF (Skp1–Cul1–F-box protein) complex, facilitates Lys29-linkage and activation of ASK1 (apoptosis signal-regulating kinase 1), and promotes type I interferon production upon viral infection." (PMID 27063938, 2016).
gastric cancer (1 paper, 2021). A primary or metastatic malignant neoplasm involving the stomach. "Decreased expression of Fbxo21 was significantly associated with poor prognosis in gastric cancer." (PMID 33531987, 2021). "Considering the important role of EMT process in cell migration and invasion, we wondered if Fbxo21 affected the gastric cancer migration and invasion via the EMT." (PMID 33531987, 2021). "Then we examined the effect of different Fbxo21 expression levels on the biological function of gastric cancer cells in vivo and in vitro." (PMID 33531987, 2021). "Fbxo21 expression was negatively correlated with Nr2f2 protein expression in gastric cancer tissues and cell lines." (PMID 33531987, 2021). "Despite the effect on antivirus immune response and ubiquitination regulation of a few oncoproteins, such as EID1 and P-gp, little is known about the Fbxo21 function in tumors, including gastric cancer." (PMID 33531987, 2021). "Then we examined the Fbxo21 expression via western blot and immunohistochemistry in specimens from gastric cancer patients." (PMID 33531987, 2021). "To confirm the role of Fbxo21 in proliferation of gastric cancer cells, we transfected Fbxo21 siRNA into SGC-7901 and BGC-823 cells, and Flag-tagged Fbxo21 expression construct into MGC-803 and MKN28 dells." (PMID 33531987, 2021). "The data showed that Fbxo21 expression was reduced in gastric cancer tissues and correlated with poor prognosis of gastric cancer patients." (PMID 33531987, 2021). "The status of Fbxo21 gene or protein would likely be a potential biomarker for clinical prognosis and an individualized clinical therapy target in gastric cancer." (PMID 33531987, 2021). "We detected Fbxo21 expression in 16 gastric cancer specimens and normal mucosa tissues after surgery using western blot and immunohistochemistry." (PMID 33531987, 2021). "The Fbxo21 protein level in gastric cancer tissues was significantly lower than that in matched normal tissues." (PMID 33531987, 2021). "Nr2f2 has been reported to play important roles in the occurrence and development of gastric cancer, and identified as one of the potential targets of Fbxo21." (PMID 33531987, 2021). "Its expression was inversely correlated with Nr2f2 protein expression in gastric cancer, and Fbxo21 regulated Nr2f2 status by inducing Nr2f2 ubiquitination and proteasomal degradation." (PMID 33531987, 2021). "In conclusion, Fbxo21 regulated the migration and invasion of gastric cancer cells." (PMID 33531987, 2021). "The results indicated that Fbxo21 status regulated the EMT phenotype of gastric cancer." (PMID 33531987, 2021). "Considering the important role of Nr2f2 in the EMT process revealed by these studies, we supposed that the Fbxo21 may regulate gastric cancer biological process via Nr2f2." (PMID 33531987, 2021). "Moreover, the data from TCGA database showed that the decrease of Fbxo21 expression in gastric cancer patients was related to the reduction of 5-year survival rate." (PMID 33531987, 2021). "Fbxo21 expression level in gastric cancer is much lower than that in normal mucosa tissues." (PMID 33531987, 2021). "Taken together, Fbxo21 functions as a tumor suppressor in gastric cancer." (PMID 33531987, 2021). "We also detected the role of Fbxo21 in the EMT of gastric cancer." (PMID 33531987, 2021). "In our study, we confirmed that Fbxo21 expression was decreased in gastric cancer tissues." (PMID 33531987, 2021). "Therefore, considering the important role of F-box family proteins in tumor progression, we are interested in the Fbxo21 expression level and function in gastric cancer." (PMID 33531987, 2021). "We determined the role of Nr2f2 in gastric cancer and the relation between Fbxo21 and Nr2f2." (PMID 33531987, 2021). "Therefore, we have confirmed that the decreased expression of Fbxo21 indicates the poor prognosis of human gastric cancer." (PMID 33531987, 2021). "This study investigated the biological role of Fbxo21 and its mechanisms in gastric cancer." (PMID 33531987, 2021).
gastric cancer (continued). "Therefore, we suggested that Fbxo21 inhibited the EMT in gastric cancer by downregulating Snail and Zeb1, two upstream transcription factors of the EMT." (PMID 33531987, 2021). "Fbxo21 may regulate cellular growth and invasiveness in this manner, and we would like to find a specific target of Fbxo21 in gastric cancer." (PMID 33531987, 2021). "Thus, we hypothesized that Fbxo21 could play a significant role as a tumor suppressor in gastric cancer." (PMID 33531987, 2021). "In addition, Fbxo21 protein expression was inversely associated with Nr2f2 protein expression in the gastric cancer tissues, but not the mRNA level." (PMID 33531987, 2021). "Thus, we confirmed that Nr2f2 was the specific ubiquitylation target of Fbxo21 in gastric cancer." (PMID 33531987, 2021). "We detected Fbxo21 expression in gastric cancer in MERAV website and found that Fbxo21 expression was much lower in gastric cancer tissues than normal mucosa." (PMID 33531987, 2021). "Thus, our data confirmed that Fbxo21 could inhibit the cell proliferation in gastric cancer." (PMID 33531987, 2021). "According to Spearman's rank correlation analysis, there was a strong negative correlation between Fbxo21 and Nr2f2 protein levels in gastric cancer tissues." (PMID 33531987, 2021). "To determine whether Fbxo21 regulates proliferation and the EMT in gastric cancer through the Nr2f2 signaling pathway, we re-expressed or knocked down Nr2f2 in Fbxo21-overexpressing MGC-803 and Fbxo21-silenced SGC-7901 cells." (PMID 33531987, 2021). "We also examined Fbxo21 protein level in seven cell lines: GES1, MKN45, SGC-7901, BGC-823, MGC-803, AGS and MKN28 cells, and found a similar trend to the results in tissue: Fbxo21 protein expression was lower in six gastric cancer cell lines, compared with GES1." (PMID 33531987, 2021).
gastric tumor (1 paper, 2021). "The xenograft mouse model experiments verified the role of Fbxo21 in gastric tumor progression in vivo." (PMID 33531987, 2021).
leukemia (1 paper, 2023). A malignant (clonal) hematologic disorder, involving hematopoietic stem cells and characterized by the presence of primitive or atypical myeloid or lymphoid cells in the bone marrow and the blood. "Utilizing AML primary patient expression data from the Microarray Innovations in Leukemia study, we determined that the expression of the E3 ligase FBXO21 is significantly downregulated in AML compared to healthy BM." (PMID 37689825, 2023). "Taken together, the data suggest that FBXO21 plays a key role leukemia progression and maintenance but has a limited role in normal hematopoiesis suggesting FBXO21 as a potential therapeutic target for drug discovery." (PMID 37689825, 2023). "Analysis of AML expression datasets revealed one of the FBOX E3 ubiquitin ligases, FBXO21, is differentially expressed in leukemia compared to normal bone marrow (BM)." (PMID 37689825, 2023).
mental disorder (1 paper, 2017). A disease that has its basis in the disruption of mental process. "No apparent evidence from the literature seems to implicate FBXO21 with mental disorders, and the observed association is probably due to the strong linkage disequilibrium with the NOS1 variant (r2=0.897)." (PMID 28195573, 2017).
Obesity (1 paper, 2021). Accumulation of substantial excess body fat. "Hence, these results indicate that FBXO21 is upregulated in the damaged area of articular cartilage in patients with knee OA and is associated with clinicopathological features, including Kellgren–Lawrence gradation, BMI, and obesity gradation." (PMID 33450132, 2021).
ovarian carcinoma (1 paper, 2021). A malignant neoplasm originating from the surface ovarian epithelium. "The low expression of FBXO21, ANP32E, and CYB5R3 was significantly associated with longer recurrence-free survival time of ovarian cancer." (PMID 34660776, 2021). "Combining TCGA ovarian cancer dataset, we identified differentially expressed marker genes that were significantly associated with prognosis of ovarian cancer, including ANP32E, STAT1, GPRC5A, EGFL6, PMP22, FBXO21, and CYB5R3." (PMID 34660776, 2021). "Furthermore, marker genes, STAT1, ANP32E, GPRC5A, and EGFL6, were highly expressed in ovarian cancer, while PMP22, FBXO21, and CYB5R3 were lowly expressed in ovarian cancer." (PMID 34660776, 2021). "Furthermore, PMP22, FBXO21, and CYB5R3 expression was significantly lower in ovarian cancer tissues compared with normal tissues." (PMID 34660776, 2021). "Furthermore, there is no report concerning the expression and role of FBXO21 and CYB5R3 in ovarian cancer." (PMID 34660776, 2021).
sarcoma (1 paper, 2023). A usually aggressive malignant neoplasm of the soft tissue or bone. "Although the expression of CNTNAP4 in this dataset had lowly expressed transcripts, the levels of CNTNAP4 interacting genes (MACF1, MLLT4, FBXO21, CASK) were found to be highly enriched in the Ki67high sarcoma cells, which was found as well to cluster with high MDM2 expression." (PMID 36599925, 2023).
cancer (2 papers, 2021 to 2023). A tumor composed of atypical neoplastic, often pleomorphic cells that invade other tissues. "Moreover, reduced Fbxo21 expression promoted cancer cell proliferation, migration and invasion, especially the EMT partially through Nr2f2 signaling pathway." (PMID 33531987, 2021). "Taken together, the data suggest targeting FBXO21 could inhibit canonical PI3K signaling and impedes growth of AML, but may also impede growth of other cancer sub-types dependent on canonical PI3K signaling." (PMID 37689825, 2023).
tumor (2 papers, 2021 to 2023). "In conclusion, we confirmed that Fbxo21 played a crucial role in tumor growth, metastasis and prognosis via Nr2f2/Snail pathway." (PMID 33531987, 2021). "In this study, we demonstrated that Fbxo21 acted as a tumor suppressor by inhibiting proliferation and anti-EMT activities." (PMID 33531987, 2021). "Silencing FBXO21 in human-derived AML cell lines and primary patient samples leads to differentiation, inhibition of tumor progression, and sensitization to chemotherapy agents." (PMID 37689825, 2023). "Previous studies on Fbxo21 mainly focused on the immune response 16.However, the role in tumor has not been clearly reported." (PMID 33531987, 2021). "FBXO21 is highly expressed in stem and progenitor (HSPC) population, the tumor initiating population in AML, but has low to no expression in mature myeloid populations." (PMID 37689825, 2023).
infection (1 paper, 2016). The state of being infected such as from the introduction of a foreign agent such as serum, vaccine, antigenic substance or organism. "Upon infection with VSV and HSV-1, the production of IL-6 and IFNβ was significantly impaired in macrophages after Fbxo21 knockdown." (PMID 27063938, 2016). "Fbxo21-/- RAW264.7 cells demonstrated significantly impaired IL-6 and IFNβ production in response to LPS treatment, transfection of poly (I:C), poly (dA:dT) and poly (dG:dC), or infection with VSV and HSV-1." (PMID 27063938, 2016). "We found that Fbxo21, by joining with Skp1-Cul1-Rbx1 (SCFFbxo21), is required for the production of inflammatory cytokines and type I IFNs upon vesicular stomatitis virus (VSV) and herpes simplex virus 1 (HSV-1) infection." (PMID 27063938, 2016). "In the presence of MG132 that blocks the degradation of Fbxo21, we found that VSV infection could not decrease Fbxo21 while HSV-1 infection could induce the expression of Fbxo21 protein 12 hr after infection, confirming that VSV and HSV-1 may differentially regulate the transcription of Fbxo21." (PMID 27063938, 2016).
FBXO21 also shares sentences with these, for which no sentence is quoted: acute kidney injury (1 paper); acute lymphoblastic leukemia (1); acute myeloid leukemia (1); intervertebral disc degeneration (1); Sepsis (1).